IDH1 (isocitrate dehydrogenase (NADP(+)) 1)
Diseases named in the same sentence as IDH1 in open-access papers (continued):
Sharing a sentence is not in itself a finding about the gene and the disease.
oligodendroglioma (continued). "Consistent with a previous report, the high predicted probability score (0.9835) indicated that the loss of H3K27me3 with ATRX positivity is frequent to IDH1-R132H Mut 1p/19q codeleted oligodendroglioma." (PMID 34020723, 2021). "A high recursive partitioning model predicted probability score (0.9835) indicated that the loss of H3K27me3 is frequent to IDH1-R132H Mut oligodendroglioma." (PMID 34020723, 2021). "Oligodendroglioma is genetically defined as a tumor confirmed to harbor either an IDH1 or IDH2 mutation along with co-deletion of chromosome arms 1p and 19q." (PMID 34675774, 2021). "All oligodendrogliomas included in the study presented IDH-1 (R132H) mutations, confirmed both immunohistochemically and molecularly." (PMID 33925821, 2021). "The percentage of oligodendroglioma samples with IDH1 mutation in our study is quite similar to those in previous studies." (PMID 32856857, 2020). "In the 4 examined oligodendrogliomas, we found that >90% of pSTAT3+ cells in the foci or in the rest of the tumour also expressed the mutated form of IDH1 R132H." (PMID 32218467, 2020). "All of the oligodendroglioma tumor samples shared driver-like mutations in IDH1, TERTp, CIC, and FUBP1." (PMID 32904945, 2020). "Enhanced proline synthesis by PYCR, supporting mitochondrial redox homeostasis, was reported in an oligodendroglioma cell line with an IDH1 mutation." (PMID 32013066, 2020). "In contrast, oligodendrogliomas carry mutated IDH1/2 cells associated with 1p/19q co-deletion and TERT promoter mutations." (PMID 33221817, 2020). "Since then, oligodendrogliomas are now characterized by a distinct molecular genotype namely the 1p19q co-deletion along with the simultaneous presence of an IDH1/2 mutation and are further graded according to their histopathological degree of malignancy." (PMID 32854646, 2020). "For instance, the diagnosis of oligodendroglioma requires that tumor harbors both an IDH1/2 mutation and a 1p/19q codeletion." (PMID 31968687, 2020). "LGGs with an IDH1 mutation and 1p19q co-deletion show oligodendroglioma histological characteristics and arise from TERT activation, mutations in CIC and FUBP1, and activating alterations in the phosphoinositide-3-kinase (PI3K) pathway." (PMID 32120790, 2020). "En bloc resection was performed and histopathological examination showed an oligodendroglioma WHO grade II with IDH1 mutation, 1p/19q codeletion, and Ki67 < 5%." (PMID 30109401, 2019). "IDH1-mutated human oligodendroglioma cells with endogenous 2-HG production also displayed increased OXPHOS activity in a xenograft mouse model." (PMID 30744183, 2019). "While 91% of oligodendrogliomas harbored the IDH1 mutation, the survival times of patients with IDH1-mut tumors were not different compared to patients with IDH1-wt tumors." (PMID 30857299, 2019). "IDH1 mutation rates are reported as 42.9%-100% in oligodendrogliomas, 46%-100% in anaplastic oligodendrogliomas, 74%-90% in A, and 27.3%-73% in anaplastic astrocytoma." (PMID 30592195, 2019). "Histopathological examination showed IDH1-mutated codeleted oligodendroglioma WHO grade III, Ki67 proliferation rate was 25%." (PMID 30109401, 2019). "FUBP1 and CIC were both mutated in only 12% (2/17) of oligodendrogliomas examined, and all had sustained a variant in IDH1." (PMID 31217899, 2019). "Of the genes already associated with the development of oligodendroglioma (IDH1/IDH2, CIC, and FUBP1), remarkably only the mutation in IDH1 (NM_005896:c.395G>A) was present in the primary O2005." (PMID 31217899, 2019). "In oligodendrogliomas, haploinsufficiency occurs with a high frequency in the context of an IDH1/IDH2 variant." (PMID 31217899, 2019).
oligodendroglioma (continued). "The reported two cases were initially diagnosed as oligodendroglioma with 1p/19q-codeletion and mutation of isocitrate dehydrogenase 1 (IDH1)-R132H." (PMID 31508376, 2019). "Oligodendroglioma exhibits a high frequency of IDH1/2 variants, particularly in cases harboring the signature genetic event, 1p/19q codeletion." (PMID 31217899, 2019). "Immunostaining was positive for glial fibrillary acidic protein (GFAP) and the mutated form of IDH1, and therefore excluded any diagnosis other than oligodendroglioma metastasis." (PMID 31248444, 2019). "The IDH1-mutation is associated with a hypermethylation phenotype, and IDH1 mutations are the earliest detectable genetic alterations in precursor low-grade diffuse astrocytomas and in oligodendrogliomas." (PMID 29713762, 2018). "In conclusion, the oligodendrogliomas can be defined, independently of their histopathological features, by the presence of both an IDH1 or IDH2 mutation and codeletion of chromosome arms 19 and 19q." (PMID 30279357, 2018). "According to these observations it is possible to conclude that oligodendroglioma have an origin similar to that of diffuse astrocytomas, that is, from glial progenitor cells and common precursor cells with IDH1/2 mutation." (PMID 30279357, 2018). "It has been shown previously that the majority of histologically classified oligodendrogliomas has a co-deletion of chromosomal arms 1p and 19q and a characteristic mutation of IDH1/2." (PMID 29631562, 2018). "The presence of an IDH1 or IDH2 mutation is also required for the diagnosis of oligodendroglioma and anaplastic oligodendroglioma." (PMID 29098416, 2018). "In one case (oligodendroglioma, IDH1-mutated and 1p/19q co-deleted), the SNP was detected in 100% of the alleles analyzed, compatible with a homozygous condition." (PMID 29535392, 2018). "Of the 18 lesions studied, there were only two (oligodendroglioma, diffuse astrocytoma) that had IDH-1 mutations." (PMID 30046944, 2018). "CIC mutations were found to be highly associated with oligodendroglioma histology, 1p/19q deletion, and IDH1/2 mutation." (PMID 30279357, 2018). "According to this new classification, oligodendrogliomas are characterized by the co-occurrence of the mutation of IDH1/2 and the 1p/19q co-deletion." (PMID 29631562, 2018). "Sequence analysis identified IDH1 R132H mutations in six of 40 (20 %) assessed brain tumors, namely in two oligodendrogliomas grade II, one oligodendroglioma grade III, two astrocytomas grade II, and one GBM." (PMID 27454254, 2016). "Case 2 and 3 are oligodendrogliomas with IDH1 mutation and 1p19q co-deletion, which progressed to anaplastic oligodendroglioma." (PMID 26524630, 2015). "Our study demonstrates for the first time that SSTR2 expression in HGGs is associated with IDH1 mutation, oligodendroglioma component, and improved PFS." (PMID 25977882, 2015). "Univariate analysis showed that TR is influenced by the following: extent of resection (EOR) (P < 0.002), ΔVT2T1 value (P < 0.001), histological diagnosis of oligodendroglioma (P = 0.017), and mutation of IDH1 (P = 0.022)." (PMID 26539503, 2015). "Frequently occurring driver mutations in oligodendrogliomas include mutations in IDH1, CIC, FUBP1, TERT promoter and NOTCH." (PMID 25694352, 2015). "Another common alteration, a heterozygote mutation of isocitrate dehydrogenase 1 (IDH1) on Arg132 (R132H), is found in about 80 % of oligodendrogliomas." (PMID 25008045, 2014). "A minor fraction of GBMs (0.8%, 2/240) contained mutations in both the TERT promoter and IDH1/2 suggesting they were treated oligodendrogliomas that were diagnosed as small cell GBMs." (PMID 24722048, 2014). "The majority of oligodendrogliomas (ODGs) exhibit combined losses of chromosomes 1p and 19q and mutations of isocitrate dehydrogenase (IDH1-R132H or IDH2-R172K)." (PMID 25277207, 2014).
oligodendroglioma (continued). "As a secondary analysis, the 69 oligodendrogliomas with 1p/19q status available were analyzed for an association with TERT promoter/IDH1/2 mutational status." (PMID 24722048, 2014). "Treatment of an oligodendroglioma cell line harboring an endogenous IDH1-R132H mutation with this inhibitor reduced growth in soft agar by 40%–60% and impeded the growth of xenograft tumors derived from that cell line in mice." (PMID 25147764, 2014). "Here, we report on the genetic, histologic and metabolic characterization of the E478 human oligodendroglioma xenograft line which carries the endogenous heterozygous IDH1-R132H mutation and provide novel insight into the metabolism of these tumors." (PMID 24252742, 2013). "A recurrent mutation affecting codon 132 of the IDH1 gene, located on chromosome 2q33, is used for differentiating oligodendroglioma-like tumors from others." (PMID 24179531, 2013). "High numbers of IDH1 point mutations at codon 132 were observed in oligodendrogliomas and oligoastrocytomas." (PMID 24179531, 2013). "In recent analyses, frequent IDH1 mutations were observed in secondary GBMs, diffuse or anaplastic astrocytomas, oligodendrogliomas, and anaplastic oligodendrogliomas." (PMID 23826216, 2013). "Remarkably, from 5 biopsies derived from IDH1-R132H-mutated high-grade oligodendroglioma specimens only one so far gave rise to the stable xenograft line described here (E478)." (PMID 24252742, 2013). "More recently, additional genetic signatures have been discovered, such as co-deletion of chromosomal arms 1p and 19q in oligodendroglioma and IDH1 mutations, where the latter is typical among low grade tumors." (PMID 23236348, 2012). "Somatic mutations affecting codon 132 of IDH1 were detected in 88% (n = 46/52) of all oligodendrogliomas." (PMID 22844452, 2012). "IDH-mutant and 1p/19q-co-deleted oligodendrogliomas are the second tumor classified as diffuse lower-grade adult glioma and are characterized by the coexistence of an IDH1 or IDH2 mutation and the deletion of the entire 1p and 19q arms, as well as a characteristic morphological appearance." (PMID 41517303, 2025). "This case review analyses 4 cases involving Chilean patients with a mutation in IDH1 with different primary malignancies: 1 recurrent oligodendroglioma, 2 malignant biliary tumours, and lastly, a G3 well-differentiated pancreatic neuroendocrine tumour (PanNET, NET G3)." (PMID 40182999, 2025). "The diagnosis of diffuse astrocytoma or oligodendroglioma (grade 2–3), traditionally based solely on histomorphological criteria, now requires the demonstration of the presence of the IDH1 or IDH2 mutation and, in the case of oligodendrogliomas, of the 1p/19q codeletion." (PMID 41517303, 2025). "The methylation of the MGMT promoter was correlated with younger patients who were aged less than 39 years (OR 2.56, 95% CI 1.48–4.43), female (OR 1.52, 95% CI 1.11–2.08) or had an IDH1 mutation (OR 15.92, 95% CI 7.30–34.75) and an oligodendroglioma diagnosis (OR 6.20, 95% CI 1.33–28.88)." (PMID 39767640, 2024). "In the univariate adjusted ORs, being younger than 39 years (OR 2.56, 95% CI 1.48–4.43), female (OR 1.52, 95% CI 1.11–2.08), having IDH1 mutation (OR 15.92, 95% CI 7.30–34.75) and an oligodendroglioma diagnosis (OR 6.20, 95% CI 1.33–28.88) were associated with MGMT methylation." (PMID 39767640, 2024). "This suggests that targeted cancer therapy using Ivosidenib could potentially alleviate the burden of seizures in patients with treatment-resistant epilepsy associated with IDH1 mutant oligodendrogliomas." (PMID 39201639, 2024). "IDH1 mutations are also frequently accompanied by loss of heterozygosity in oligodendrogliomas." (PMID 39529768, 2024). "In the univariate adjusted ORs, being young (OR 2.56, 95% CI 1.48–4.43), being female (OR 1.52, 95% CI 1.11–2.08), having IDH1 mutation (OR 15.92, 95% CI 7.30–34.75) and an oligodendroglioma diagnosis (OR 6.20, 95% CI 1.33–28.88) were associated with MGMT methylation." (PMID 39767640, 2024).
oligodendroglioma (continued). "Since IDH1 (R132H) mutations and histomorphological features of oligodendroglioma were preserved upon tumor recurrence, it is tempting to speculate that the tumor evolution of this case was reflected by DNA methylation changes over time." (PMID 36739454, 2023). "R132H mutation of IDH1 is the most frequent genetic alteration in oligodendroglioma." (PMID 37533228, 2023). "In addition, 1p/19q codeletion and IDH1 or IDH2 mutation are typical molecular features in oligodendroglioma." (PMID 35372027, 2022). "Furthermore, these cases harbored an activating IDH1 mutation supporting the histopathological diagnosis of oligodendroglioma." (PMID 35372034, 2022). "IDH1 mutational status was assessed by immunohistochemistry in 90 of 102 patients (88.2%), and the 1p19q codeletion status was determined in all patients with a histological diagnosis of oligodendroglioma." (PMID 36180501, 2022). "Interestingly, a recent investigation including a longitudinal study of brain tumor patients harboring the IDH1 mutation that received RT reported how 2HG levels decreased over time in oligodendroglioma patients under treatment." (PMID 36353533, 2022). "The third patient was ctDNA-positive for the R132C mutation and had a recurrent grade II oligodendroglioma progressing after radiotherapy, where the primary tumor biopsy from 7 years earlier (the last surgery that had been performed) harbored two IDH1 mutations (R132H and R132C)." (PMID 35740557, 2022). "In addition, 1p/19q co-deletions are common in oligodendrogliomas that harbor a mutation in isocitrate dehydrogenase 1 (IDH1)." (PMID 36068196, 2022). "1p/19q loss has been found to occur with IDH1 mutations in oligodendrogliomas." (PMID 35538578, 2022). "The presence of IDH1 mutations in conjunction with 1p/19q-codeletions may indicate a positive prognosis in oligodendroglioma patients treated with adjuvant PCV following radiation therapy." (PMID 34587990, 2021). "A loss of H3K27me3 was observed in 36/40 (90%) of IDH1-R132H Mut oligodendroglioma." (PMID 34020723, 2021). "High MET uptakes in IDH1-mutant oligodendrogliomas may cause low specificity for the differential diagnosis." (PMID 32382870, 2020). "Following a diagnosis in December 2014 of a right temporoparietal grade III oligodendroglioma with IDH1 mutation and 1p/19q codeletion, he underwent emergency surgical cerebral decompression for a comatose state secondary to brain herniation, with incomplete resection due to massive cerebral edema." (PMID 31248444, 2019). "In addition, oligodendrogliomas show a high frequency of isocitrate dehydrogenase 1 (IDH1 R132H) mutation in addition to 1p/19q co-deletion." (PMID 29908563, 2018). "In addition to 1p/19q co-deletion, it has become well recognized that mutations in IDH1/2 are present in the vast majority of oligodendrogliomas." (PMID 28388591, 2017). "Three GBM-O samples had IDH1 (p.R132H) mutations; two of these also demonstrated 1p/19q co-deletion and had a proneural transcriptional profile, a molecular signature characteristic of oligodendroglioma." (PMID 26757882, 2016). "Moreover, oligodendrogliomas with 1p19qLOH and/or IDH1 mutated tumors virtually cannot be propagated in vitro." (PMID 25694352, 2015). "However, in human beings, a common driving mutation in oligodendroglioma development is IDH-1 mutations, which may also be present occasionally in canine oligodendroglioma." (PMID 40417366, 2025). "The second finding of particular interest was the positive association between SSTR2 expression and IDH1 mutation, oligodendroglioma component, and improved PFS, which indicates that SSTR2 expression may become a new biomarker in HGG useful for prognostication and therapeutic decision-making." (PMID 25977882, 2015). "Pharmacologic inhibition of acid ceramidase with SABRAC preferentially reduced viability in human IDH1-mutant oligodendroglioma cell lines." (PMID 41928812, 2026).
oligodendroglioma (continued). "Together, these findings suggest that IDH1-mutant oligodendroglioma harbors a pre-existing heightened sensitivity to ceramide stress and identify acid ceramidase as a therapeutically actionable target in this disease." (PMID 41928812, 2026). "We previously showed that in IDH1-mutant oligodendroglioma, the oncometabolite D-2-hydroxyglutarate biases the sphingosine-1-phosphate-to-ceramide rheostat toward ceramides." (PMID 41928812, 2026). "Recurrent molecular genetic alterations, such as IDH1/2, FUBP1, CIC, and TERT promoter mutations, have been identified to co-occur with 1p/19q co-deletion in oligodendrogliomas." (PMID 40426960, 2025). "Specifically, we used TS603 (an oligodendroglioma cell line with the IDH1‐R132H mutation) and HT1080 (a fibrosarcoma cell line with the IDH1‐R132C mutation)." (PMID 40171868, 2025). "The diagnosis was grade 2 IDH1 R132H mutant, 1p/19q codeleted oligodendroglioma with the following histomolecular characteristics: Ki‐67 < 5%, absence of mitoses, necrosis, or microvascular proliferations, pTERT mutant, and CDKN2A/B intact." (PMID 40956046, 2025). "according to modern WHO standards, explicitly used molecular data, comparing IDH1-mutant astrocytomas against oligodendrogliomas which were, by definition, also IDH-mutant and 1p/19q co-deleted." (PMID 41168559, 2025). "1p/19q co-deletion was detected by fluorescence in situ hybridization (FISH) and Tempus xT 648 gene panel reported genomic variants in IDH1, TERT, CIC, and FUBP1, as expected for an oligodendroglioma." (PMID 39857783, 2025). "Pseudoprogression in human oligodendroglioma is also reported to occur in both IDH-1 wild-type and mutant oligodendrogliomas." (PMID 40417366, 2025). "By contrast, IDH1/2-mutant 1p/19q codeleted oligodendrogliomas showed higher concordance with their histopathologic designation (84.8% originally classified as oligodendrogliomas)." (PMID 39164213, 2025). "Subtype-specific localization was most prominent in oligodendrogliomas, where 80.8% of IDH1/2-mutant/1p19q-co-deletion tumors originated in the frontal lobe compared to 32.1% of IDH1/2-wild-type GBM." (PMID 41377022, 2025). "More specifically, the highest number of patients with IDH1 mutation in tissue was found in the anaplastic astrocytoma group (38.1%), following by diffuse astrocytoma (23.8%), GBM (14.3%), oligodendroglioma (14.3%), and oligoastrocytoma (9.5%)." (PMID 38172718, 2024). "In addition, alpha thalassemia/mental retardation syndrome X-linked (ATRX) mutations may follow a similar pattern in diffuse astrocytomas, while telomerase reverse transcriptase (TERT)-promoter mutations and 1p19q deletions in conjunction with IDH1 mutations are associated with oligodendrogliomas." (PMID 39529768, 2024). "A case study also showed the potential of Ivosidenib in improving seizures in a patient with drug-resistant epilepsy due to an IDH1-mutant grade 2 oligodendroglioma." (PMID 39201639, 2024). "Oligodendroglioma is characterized mainly by the presence of alterations in the IDH1/2 sequence and chromosomal codeletion of 1p/19q." (PMID 39768176, 2024). "This case study presents an oligodendroglioma, the isocitrate dehydrogenase 1 (IDH1) mutant, 1p/19q-codeleted tumor with bone marrow metastasis." (PMID 39061087, 2024). "Recently identified molecular markers, including the non-reciprocal translocation resulting in a 1p/19q codeletion, and mutations in the IDH1 or IDH2 gene, have significantly enhanced our understanding and characterization of oligodendrogliomas." (PMID 39061087, 2024).